CFH (complement factor H)
Diseases named in the same sentence as CFH in open-access papers (continued):
Sharing a sentence is not in itself a finding about the gene and the disease.
Alzheimer disease (18 papers, 2009 to 2025). A progressive, neurodegenerative disease characterized by loss of function and death of nerve cells in several areas of the brain leading to loss of cognitive function such as memory and language. "The IFN-γ-induced expression of c-fos in astrocytes regulates the complement factor H, whose abnormal levels instead induce neuronal loss in pathologies such as Alzheimer’s disease." (PMID 35741573, 2022). "We have previously shown that a common missense variant in another complement gene, CFH, conferred genetic risk to Alzheimer's disease, whereas this variant underwent pathogen-driven selection so that it was retained in the population due to the trade-off effect." (PMID 31032141, 2019). "The shared pathologies, such as the presence of amyloid-beta in drusen in AMD patients, and common risk factors, including aging and genetic variants in CFH and ApoE4 in AMD and Alzheimer’s disease, suggest potential overlap in disease pathogenesis." (PMID 41008535, 2025). "Our previous study pointed out that increased level of CFH mRNA is positively correlated with severity of Alzheimer’s disease (AD), and CFH results in structural change of the atrophy rate and entorhinal cortex during AD progression." (PMID 37520223, 2023). "It has also been found that increased concentrations of complement 3 and CFH in the cerebrospinal fluid (CSF) of Parkinson’s disease, Alzheimer’s disease, and multiple-system atrophy patients correlated with disease severity." (PMID 32157596, 2020). "Our results strongly suggest the active roles of C7, together with other complement components such as the GWAS hits CR1, CLU and CFH, in the development of Alzheimer's disease." (PMID 31032141, 2019). "CFH has also been reported to be a direct target of miR-146a and potentially important in inflammation in Alzheimer's disease." (PMID 22363497, 2012). "In Alzheimer’s disease brain, up-regulation of has-miR-146a is found in inverse relationship with the down-regulation of its target gene, complement factor H (CFH), which is an important repressor of inflammatory response in the brain." (PMID 19881911, 2009). "In Alzheimer's disease (AD), CFH has been shown to be significantly downregulated and might be a candidate plasma biomarker." (PMID 29590637, 2018). "We measured complement factor H, a component of the complement system and biomarker for Alzheimer's disease progression, and tau phosphorylation at the serine 235 site, hyperphosphorylated forms of tau being a defining neuropathological hallmark of the disease." (PMID 23153828, 2013). "Experimentally proven targets of miR-146a include complement factor H (CFH), interleukin-1 receptor-associated kinase-1 (IRAK1) and TNF receptor-associated factor 6 (TRAF6), all associated with innate immunity and inflammatory pathways which are dysregulated in Alzheimer's disease." (PMID 24133413, 2013). "A recent study has shown that the NF-κB-regulated microRNAs miR-9, miR-125b, miR-146a, and miR-155 are upregulated in both AMD and Alzheimer's disease and that miR-146a and miR-155 target the 3′-UTR of CFH, thereby downregulating CFH." (PMID 23244519, 2012). "Aberrant expression of miR-146a which is downregulated by γ-synuclein is implicated in breast cancer, Huntington disease, Alzheimer’s disease and aged related macular degeneration (AMD) which might be explained by targeting and downregulation of the complement factor H (CFH)." (PMID 24040069, 2013).
geographic atrophy (18 papers, 2007 to 2025). "The CFH Y402H polymorphism (rs1061170) was present in 13 geographic atrophy patients and 1 control patient." (PMID 35882847, 2022). "Several studies have previously examined the role of CFH Y402H polymorphism in the AMD subtypes such as geographic atrophy (GA) or choroidal neovascularization (CNV)." (PMID 23922956, 2013). "Clinical trials targeting proteins encoded by the AMD-associated genomic loci C3, CFB, CFI, CFH, and ARMS2/HTRA1 are currently ongoing, and a phase III clinical trial for C3 inhibition recently showed a modest reduction of lesion growth in geographic atrophy." (PMID 36108770, 2022). "CFH, ARMS2/HTRA1 and C3 genes have been reported to increase the risk of progression from intermediate drusen to large drusen and from large drusen to geographic atrophy and neovascularization." (PMID 25893111, 2015). "Here, we analyzed association between variants in CFH, C3 and ARMS2 and disease progression of geographic atrophy (GA) due to AMD." (PMID 19823576, 2009). "Our data also makes a case for CFH to have a role in drusen formation and progression as well as the development of late complications, such as choroidal neovascularization or geographic atrophy." (PMID 18043728, 2007). "Genes with common risk alleles associated with geographic atrophy and neovascular AMD were upregulated in geographic atrophy RPE cells, including CFH, HTRA1, EFEMP1, and APOE, which provide further evidence of their involvement in the pathogenesis of geographic atrophy." (PMID 35882847, 2022). "Thus the IF data from two different CFH 402H (H/H) donors suggest that CFH and Fib3 are colocalized rather specifically in substructures in soft drusen in an eye with geographic atrophy and an H/H genotype." (PMID 23840815, 2013). "Alterations to complement factor H (CFH) and complement factor D (CFD) have been related to both conditions, ARMD and geographic atrophy." (PMID 34204630, 2021). "Our data confirm the association between advanced AMD (both geographic atrophy and CNV) and the 10q26 SNPs rs11200638 (HTRA1 promoter) and rs10490924 (LOC387715/ARMS2 A69S), independent of the CFH Y402H polymorphism." (PMID 18682806, 2008). "We genotyped three SNPs, rs1061170 (exon 9, CFH), rs11200638 (HTRA1 promoter, −512 bp), and rs10490924 (6.6 kb upstream of HTRA1 in LOC387715/ARMS2) in 333 cases with advanced AMD (choroidal neovascularization [CNV] and geographic atrophy) and 171 age-matched examined controls." (PMID 18682806, 2008).
lung cancer (18 papers, 2012 to 2025). A malignant neoplasm involving the lung. "It has been shown that CFH is upregulated in lung cancer, and that this overexpression is associated with larger tumors, lymph node metastases, and worse overall survival." (PMID 38389705, 2024). "The first report of the association of CFH with cancer was published in 1998 where it was demonstrated that the presence of CFH on lung cancer cells makes them resistant to complement mediated lysis." (PMID 38389705, 2024). "Recently, it has been shown that complement factor H Y402H polymorphism interact with cigarette smoking to confer the susceptibility to lung cancer." (PMID 24621201, 2014). "Further analysis showed that the risk increased with higher cumulative smoking doses, which suggests that the CFH Y402H polymorphism may interact with cigarette smoking and amplify lung cancer development risk in the Chinese population." (PMID 40612949, 2025). "CFH is important for the development of lung cancer, but this gene may be associated with the progression of BRCA." (PMID 31311202, 2019). "Thus, STAT4 activation causes CFH overexpression that allows lung cancer cells to escape from complement-mediated immune system attack." (PMID 30987235, 2019). "Complement factor H is generally associated with a large variety of diseases, particularly lung adenocarcinoma, and an over-representation of several genotypes of this gene have been previously linked to an increased risk of lung cancer and smoking." (PMID 27341628, 2016). "STAT4 regulates complement factor H (CFH) in lung cancer, which inhibits the complement system and mediates resistance to therapy with monoclonal antibodies, which generally enhances complement activation leading to cellular cytotoxicity." (PMID 34638338, 2021). "STAT4 overexpression in lung cancer leads to overexpression of CFH, which then mediates inadequate therapy response." (PMID 34638338, 2021). "GT103 is a fully human anti-CFH monoclonal antibody currently in a Phase Ib clinical trial for advanced lung cancer (clinicaltrials.gov)." (PMID 34133431, 2021). "Autoantibodies to CFH in cancer were first discovered in the blood of patients with early stage, non‐metastatic non‐small cell lung cancer (NSCLC)." (PMID 33708358, 2020). "A study in lung cancer has shown tumour cells that express CFH can prevent complement activation in vivo and protect tumour cells from complement‐mediated cytolysis, thereby promoting tumour development (Ajona, Hsu, Corrales, Montuenga, & Pio, 2007)." (PMID 33708358, 2020). "Similar to NF-κB, IL-1β and oxidative stress are usually prominent in cancer cells, but the upregulation of miRNA-146a by these factors cannot explain the high expression of CFH in lung cancers." (PMID 30987235, 2019). "Altogether, this result revealed that CFH overexpression in A549 cells and lung cancer tissue is under the control of STAT4 activation, which is known to be mediated by the JAK and SOCS cytokine signaling pathway." (PMID 30987235, 2019). "Here, we studied the factors that influence CFH overexpression and their related mechanisms in lung cancer." (PMID 30987235, 2019). "Next, to investigate any correlation between CFH expression and the expression of STATs in human normal lung tissues and lung cancer tissues, the transcription level of CFH was compared with STAT1, STAT3, and STAT4." (PMID 30987235, 2019). "First, signal transducer and activator of transcription 4 (STAT4) expression patterns coincided with CFH expression patterns in lung cancer tissues." (PMID 30987235, 2019). "Hypomethylation of the STAT4 regulatory region can activate the JAK/STAT4 pathway, resulting in CFH overexpression in lung cancers." (PMID 30987235, 2019). "In conclusion, our results highlighted that CFH overexpression in lung cancer is due to the demethylation of the STAT4 regulatory region, resulting in its over expression, which may be activated by the JAK/STAT pathway negatively controlled by SOCS-1 proteins." (PMID 30987235, 2019).
lung cancer (continued). "The upregulated proteins CFH and Hpt are rather non-specific diagnostic makers for lung cancer diseases." (PMID 30923558, 2019). "In this study, we investigated the signaling mechanism that elicits CFH expression in lung cancer." (PMID 30987235, 2019). "A recombinant antibody against CFH has been shown to induce a conformational change in CFH, promote complement-mediate cytoxicity on cancer cells in the culture, and inhibit tumor growth in a mouse lung cancer model." (PMID 31331124, 2019). "Knockdown of STAT4 led to decreased CFH secretion from lung cancer cells." (PMID 30987235, 2019). "We found that CFH was highly expressed in human lung cancer cells and tissues." (PMID 30987235, 2019). "In addition, a low level of suppressors of cytokine signaling (SOCS)-1/3, a Janus kinase (JAK) inhibitor, was observed in lung cancer cells and its transfection decreased CFH protein levels and promoter activity." (PMID 30987235, 2019). "We have shown that STAT4 is responsible for the upregulation of CFH in lung cancer cells." (PMID 30987235, 2019). "Our study demonstrated that STAT4 stimulates CFH upregulation in lung cancers." (PMID 30987235, 2019). "Similarly, increased levels of other extravasated plasma proteins, such as complement factor H or albumin, were previously observed in bronchial fluids from lung cancer patients." (PMID 25799154, 2015). "Importantly, the increased cancer risk associated with CFH variants was evident among smokers but not non-smokers, suggesting a smoking-related genetic risk factor for lung cancer." (PMID 40612949, 2025). "Therefore, we hypothesized that overexpression of CFH in lung cancer is the result of upstream factors that are involved in cytokine signaling, dysregulating the activity of STAT4." (PMID 30987235, 2019). "This might indicate that STATs are a key regulator of CFH expression in human lung cancer." (PMID 30987235, 2019). "Importantly, lung cancer cells demonstrate a high level of resistance to complement-mediated lysis via activation of the classical pathway, as well as via the alternative pathway due to the role of CFH and FHL-1." (PMID 30987235, 2019). "To prove that CFH is the target of GT103 in EVs, we probed a western blot of EVs purified from the conditioned media from the CMT167 murine lung cancer cell line and two CFH CRISPR/Cas9 knockout derivatives." (PMID 34133431, 2021). "In conclusion, our results demonstrated that CFH is upregulated by constitutive activation of STAT4, which is accounted for by SOCS silencing in lung cancer cells." (PMID 30987235, 2019). "STAT1 and STAT3 were also tested because STAT1 was reported to be a transcription factor for CFH in response to the stimulation of IFN-γ, and STAT3 is an oncogene that is also reported to be increased in lung cancers." (PMID 30987235, 2019). "We also showed that phosphorylated STAT4 and CFH expression were decreased by STAT4 knockdown, indicating that CFH expression levels are regulated by STAT4 in lung cancer." (PMID 30987235, 2019). "There has been no report that describes the molecular mechanisms of CFH overexpression in lung cancers." (PMID 30987235, 2019). "We demonstrated that CFH expression levels are highly correlated with STAT4 expression levels in human lung cell lines and human lung cancer tissues without any stimuli." (PMID 30987235, 2019).
thrombotic microangiopathy (18 papers, 2013 to 2025). The syndromes of microangiopathic hemolytic anemia, thrombocytopenia, and variable signs of organ impairment, due to platelet aggregation in the microcirculation. "CFH gene mutations and anti-CFH autoantibodies disrupt the function of CFH and lead to thrombotic microangiopathy predominantly in the glomerular capillary bed." (PMID 37905269, 2023). "We report the case of a patient with complement factor H gene variant, who developed thrombotic microangiopathy on a mixed clinical background." (PMID 34733563, 2021). "VEGF-A inhibition decreased the renal level of inhibitory complement factor H (CFH), in which genetic variants were known to be features of hereditary thrombotic microangiopathy, suggesting that VEGF-A is involved in local regulation of the complement system." (PMID 28835895, 2017). "Complement factor H (fH) is a plasma protein that regulates activation of the alternative pathway, and mutations in fH are associated with a rare form of thrombotic microangiopathy (TMA), known as atypical hemolytic uremic syndrome (aHUS)." (PMID 23991205, 2013). "Of note, a case report demonstrated that the pathogenic nature of IgG4 autoantibodies directed against CFH could trigger the C’-mediated thrombotic microangiopathy in a patient carrying a genetic predisposition for homozygote CFHR1/4 gene deletion." (PMID 36834989, 2023). "The presence of this microarray on chromosome 1 may be associated with the production of antibodies to factor H complement (CFH) and activation of the complement system through an alternative pathway with endothelial damage and, consequently, the development of thrombotic microangiopathy." (PMID 37626703, 2023). "The mere presence of anti-CFH is not sufficient for the florid presentation of aHUS, but multiple hits are required for full-blown thrombotic microangiopathy, which could explain the indolent nature of the disease in our patient." (PMID 39184759, 2024).
dense deposit disease (16 papers, 2006 to 2023). "Further identified heterozygous polymorphisms in the patient included the CFH Y402H risk factor for dense deposit disease, as well as the CD46 rs2796267, rs2796268 and rs1962149 polymorphisms, referred as part of the MCPggaac risk haplotype for aHUS." (PMID 34248927, 2021). "In patients with MPGN type II, or dense deposit disease, CFH mutations and disturbed serum complement activation levels have also been demonstrated." (PMID 22933840, 2012). "Dense deposit disease (formerly membranoproliferative glomerulonephritis type II) and C3 glomerulonephritis are also associated with uncontrolled complement activation and mutations in CFH or CFI have been described." (PMID 22834933, 2012). "N-terminal mutations in CFH and antibodies targeting this moiety appear to induce a Dense-deposit disease phenotype while C-terminal mutations and antibodies cause the development of HUS phenotype." (PMID 22934182, 2012). "The drusen in dense deposit disease may be associated with monogenic disease due to mutations in CFH, C3 or CFB25." (PMID 36316518, 2022). "This is best exemplified in dense deposit disease caused by CFH mutations." (PMID 36316518, 2022). "On the other hand, patients afflicted with membranoproliferative glomerulonephritis type 2 (MPGN2), a renal disease that is also associated with CFH mutations, show AMD-like features." (PMID 28275964, 2018). "They applied prior biological knowledge of the involvement of CFH (also called HF1) in membranoproliferative glomerulonephritis type II (MPGNII), a disease in which patients develop ocular drusen nearly identical to those found in AMD patients." (PMID 25032678, 2014).